IFNG (interferon gamma)
Diseases named in the same sentence as IFNG in open-access papers (continued):
Sharing a sentence is not in itself a finding about the gene and the disease.
tumor (continued). "PD-L1 is an IFNγ-responsive gene, and high PD-L1 expression indicates the existence of high levels of tumor antigen-specific IFNγ-secreting T cells." (PMID 31942188, 2020). "The authors demonstrated that the activation of the NK natural cytotoxic receptor 1 (mouse) and NKp46 (human) induces IFNγ production which, in turn, modulates fibronectin 1 expression on tumor cells, preventing metastatic spread." (PMID 32423420, 2020). "This production of lactate in tumor cells impacts interferon-gamma production by tumor-infiltrating T cells, NK activation, and the proportion of myeloid-derived suppressor cells." (PMID 33177494, 2020). "As expected, IFNγ+ CD8+ T cells were significantly lower in the T-regHi tumor samples than in the T-regLo ones." (PMID 32554190, 2020). "IFNγ is the main mediator of PD-L1 upregulation on tumor cells and is released by CEA-TCB activated T cells in co-culture with tumor cells." (PMID 33330050, 2020). "IFNγ secreted by early dysfunctional T cells was responsible for the progressive expression of PD-L1 induced on tumor cells, which in turn became able to convert effector CD8 T cells into dysfunctional cells." (PMID 32707692, 2020). "Local suppression of IL-17a in the lung of a model with lung cancer showed improved anti-tumor immunity featured by the enhanced IFNγ, a reduced number of T-regulatory cell and the inhibited tumor growth." (PMID 32554855, 2020). "IFNγ is released by activated T cells upon recognition of tumor neoantigens and activates IFNγ-JAK-STAT-IRF1 axis in tumor cells." (PMID 32258038, 2020). "Treatment with 5-FU triggered the apoptosis of MDSCs, promoted tumor-infiltrating T cells to produce high levels of IFNγ and enhanced the T cell-dependent antitumor response in the mouse EL4 model." (PMID 32942545, 2020). "The altered T cell ratio resulted from a significant reduction in CD8+ T cells expressing granzyme B and IFNγ and from a significant expansion of CD39hiCD38hiPD-1hiCTLA4hiFoxp3hi Tregs at the tumour site." (PMID 32333046, 2020). "Hereby, we show that the tumor endothelial cells up-regulate IDO1 upon CD40-stimulating immunotherapy in response to increased IFNγ-secretion by T-cells, revealing a novel immunosuppressive feedback mechanism whereby tumor vessels limit T-cell activation." (PMID 32231867, 2020). "Given that LIGHT-mediated changes to the TME facilitate the shift from a cold to a hot tumor phenotype, IFNγ levels also rise." (PMID 32499782, 2020). "Our previous studies indicated that chemoradiotherapy-damaged tumor cells release IFNγ, which remarkably promotes the upregulation of PD-L1 expression." (PMID 32079180, 2020). "Tumor-infiltrating CD8s are largely activated, expressing cytotoxic effectors such as Perforin and Granzyme B (including plentiful IFNγ), which are scarce in murine CD8s located in lymphoid organs at homeostasis." (PMID 32322254, 2020). "IFNγ induces the expression of PD-L1 on the tumor-cell surface and therefore blocks NK/ILC1-cell maturation and activity." (PMID 33138017, 2020). "The relative mRNA levels of IFNγ were found to be undetectable in tumor-free animals, so this component is normalized to the tumor-bearing vehicle-treated group to allow a partial analysis." (PMID 32722688, 2020). "This resulted in a significant increase in cell lysis and IFNγ production in the tumor containing co-culture as measured by LDH cytotoxicity assay when compared with autologous monocytes (p = 0.030 and p = 0.003, respectively)." (PMID 32867034, 2020). "The level of tumor infiltrating human T cells expressing intracellular IFNγ was evaluated in HTB-1 tumors." (PMID 32373533, 2020). "In both models, VISTA blockade inhibited tumor growth and improved proliferation, activation, and anti-tumor activity of T cells (increased IFNγ, granzyme B, CD107)." (PMID 32679922, 2020).
tumor (continued). "Combination with anti–CTLA-4 led to tumor regression accompanied by enhanced T cell activity, increase in activated CD86+ monocytes in the tumor, augmentation of pro-inflammatory IFNγ, TNFα, and IL-6 and decrease in immunosuppressive MCP-1 and IL-10 cytokines." (PMID 32793228, 2020). "The rate of IFNγ-secreting cells in response to stimulation with the tumor antigen (OVA peptide) was similar between the two groups of treatment." (PMID 32290265, 2020). "Radiation can directly induce upregulation of PD-L1 on tumor cells, and also act as an adaptive resistance mechanism for T cells to release IFNγ in tumor microenvironment." (PMID 33469538, 2020). "Interferon gamma (IFN-γ) is the major PD-L1 regulation factor in tumor cells and reflects ongoing antitumor immune activity." (PMID 33659213, 2020). "We also measured the tumor levels of IL-12 and IFNγ proteins, which can overcome the suppressive tumor microenvironment and shift the balance to favor CD8+ T cell antitumor immunity." (PMID 31208461, 2019). "As a consequence of elevated numbers of these cells in tumor, an increased amount of interferon gamma (IFN-γ) and granzyme B is observed." (PMID 31035592, 2019). "PD-L1 expression on tumor cells is estimated to reflect the interaction between tumor and immune cells in the tumor microenvironment, partially due to the induction of PD-L1 expression by IFNγ from activated T cells." (PMID 30796310, 2019). "By doing so, we showed that tumor spheroids can be infiltrated by allogeneic activated/memory T and NK cells which induce tumor cell death and spheroid destruction, notably through IFNγ and NKG2D-MICA/B pathways." (PMID 30871626, 2019). "In melanoma, the impaired IFNγ expression in tumor-infiltrating T cells and NK cells, along with LDHA activity associated lactate production, promotes tumor growth by exerting an immunosuppressive phenomena." (PMID 31546918, 2019). "We also computed the individual signature of 12 previously identified tumor infiltrating immune cells, thus including a total of 18 cell type-specific signatures plus two signatures for the interferon gamma response pathway 33,36–39." (PMID 31044160, 2019). "Using an immunocompetent mouse model of NSCLC, this study demonstrates that tumor-intrinsic response to IFNγ determines response to anti–PD-1 through alterations in the tumor microenvironment." (PMID 31133614, 2019). "When analyzing spleen cells from tumor-bearing mice at day 15–17 p.i., we detected similarly significant changes in Tnfα, Ifnγ, and Nos2 expression and a significant increase in Sgk1 expression." (PMID 31214164, 2019). "After tumor cell challenge, IL-30 conditional KO mice showed an imbalance towards a Th1-type immune response, as revealed by IFNγ and IL-12 expression in splenic lymphocytes and macrophages." (PMID 31366386, 2019). "Inhibition of VEGFA and Ang-2 normalizes tumor vessels and increases IFNγ+ CD8+ T cells’ extravasation and accumulation, which further enhances the antitumor effects of PD-1 inhibitors." (PMID 31835465, 2019). "Typically, inflamed tumors show a pre-existing antitumor immune response with abundance of tumor-infiltrating lymphocytes (TILs), IFNγ-producing CD8+ T-cells and high expression of PD-L1." (PMID 31125352, 2019). "Depletion of each single component of the NK cell-IFNγ-TRAIL axis promoted tumor growth in a chemical-induced murine sarcoma model illustrating its importance in antitumor responses." (PMID 31333662, 2019). "As shown, in the presence of tumor antigen (irradiated tumor cells), IFNγ-producing T cells dramatically increased in the β-lap treatment group." (PMID 31324798, 2019). "Tumor elimination involves a synergistic effect of the combination that significantly boosts T cell cytotoxicity, IFNγ production, T cell proliferation, migration, and glycolysis." (PMID 31307539, 2019). "A gene set enrichment analysis revealed a significant increase of IFNγ-response and JAK/STAT pathway activation in tumor associated astrocytes." (PMID 31186414, 2019).
tumor (continued). "The high levels of IFNγ were also accompanied by increased levels of PD-L1 and PD-L2 in tumor cells." (PMID 30992475, 2019). "Tumour infiltrating T cells isolated 3 weeks after TC-1 tumour transplantation, secreted less IFNγ, perforin and Granzyme B compared with those isolated 2 weeks after TC-1 tumour inoculation." (PMID 31277636, 2019). "Consistent with the cytotoxic activity, Ly6C+CD8+ population from EMT6 tumor-primed mice expressed higher levels of IFNG, GZMA, GZMB, and PRF1 as assessed by qPCR analyses." (PMID 30926774, 2019). "Tumor lymphocyte and NK cell infiltration and IFNγ upregulation, have been proposed as potential predictors of response alongside mutational burden, however these need to be standardized and widely evaluated in clinical practice." (PMID 30941125, 2019). "Expression of IFNG, CD30, CXCL13, and PRF1 was associated with increased level of immune infiltrates (CD8+ T cells, dendritic cells, and neutrophils) within the tumor." (PMID 31998644, 2019). "Another group found that while there were detectable T cell responses to tumor-associated antigens, responses declined with advancing disease and tumor antigen-specific CD8+ T cells were dysfunctional with low production of IFNγ, Granzyme B, and perforin." (PMID 31627733, 2019). "For instance, dihydroartemisinin was reported to inhibit tumor tissue, increase the level of interferon-gamma (IFN-γ), and decrease interleukin 4 (IL-4) in tumor-bearing mice." (PMID 31892257, 2019). "According to this possibility, Th17 cells are positively associated with effector immune cells, including cytotoxic CD8+ T cells, NK cells, and IFNγ-producing Th1 cells in the tumor microenvironment in vitro and human." (PMID 31024835, 2019). "This compensatory PD-L1 induction mediated by IFNγ inhibits the anti-tumor activity of T cells which is a key mechanism of adaptive immune resistance." (PMID 30873179, 2019). "Transcriptome profiling and gene ontology biological analysis confirmed that Mφ-PD-L1+ HCC tumor samples displayed an immune-activated microenvironment and upregulated genes that were mainly involved in the IFNγ-mediated signaling pathway." (PMID 31727135, 2019). "Taken together, the DCG spore treatment increases the levels of proinflammatory cytokines at the tumour site and attracts IFNγ/IL-9 secreting T cells to the tumour." (PMID 31183361, 2019). "To explore this possibility, we first examined the effect of adapter dose on tumor cell lysis and IFNγ release in vitro." (PMID 31213606, 2019). "Mouse CD80+PD-L1+ tumor cells similarly maintained IFNγ production by activated PD-1+ mouse T cells." (PMID 31001479, 2019). "(D) Overview of high-scoring components of the tumor-immune synapse and IFNγ signaling pathway recovered by the screen." (PMID 31452512, 2019). "Of note, such dual therapies were shown to not only augment intra-tumoral presence of DCs and tumor-specific CD8+ T cells but also the fraction of intra-tumoral CD4+ or CD8+ T cells producing IFNγ as well as the levels of IFNγ in the TME." (PMID 31244820, 2019). "The magnitude of the cytokine release was markedly higher in HPK1 KD groups, with over 30 fold higher levels of IFNγ in the tumor bearing mice compared with naïve mice." (PMID 30913212, 2019). "The superior anti-tumour effect of TH1 cells is reflected by a large amount of IFNγ secretion, which is responsible for priming and enhancing CD8 T-cell response." (PMID 31434983, 2019). "Specifically, CD11b+CD103− DC predominate in PDA, express high IL-23 and TGF-β, and induce FoxP3neg tumor-promoting IL-10+IL-17+IFNγ+ regulatory CD4+ T cells." (PMID 30926808, 2019). "Conversely, IFNγ blockade in our system resulted in decreased spheroid destruction, tumor cell apoptosis and spheroid infiltration by immune cells compared to control conditions." (PMID 30871626, 2019).
tumor (continued). "Intravenous administration of the derivative of Clostridial ghonii (DCG) spores leads to both tumour and systemic inflammatory responses characterized by increased IFNγ/IL-9 secreting T cells in the spleen and the tumour." (PMID 31183361, 2019). "An IFNγ-dependent modulation was evident also for PD-L2, in two out four tumour cell lines assessed." (PMID 30723303, 2019). "MEK-I modulates in–vitro the immune micro-environment through a transcriptionally decrease of PD-L1 expression, enhance of MHC-I expression on tumor cells, increase of the production of several cytokines, like IFNγ, IL-6, IL-1β and TNFα." (PMID 31196138, 2019). "We thus measured OVA‐specific responses 7 days after the second VSV‐GP or DCVacc single and combination treatments in spleen and tumor tissue by measuring IFNγ‐producing CD8 T cells after in vitro OVA‐peptide stimulation." (PMID 30972741, 2019). "IFNγ released by CD8+T cells promotes the tumor expression of MHC class 1 antigens thereby making tumors susceptible to immune cell detection and elimination." (PMID 30979375, 2019). "The presence of tumor cells induced production of IFNγ by NK cells, and this was significantly reduced when the malignant cells previously had encountered platelets (MCF-7, p = 0.0177; HCT 116, p = 0.0006; both Student’s t test)." (PMID 30813611, 2019). "At higher co-culture ratios of B to T cells, the T cells cultured with B cells derived from tumor draining lymph nodes of cobimetinib treated mice also exhibited more interferon-gamma and granzyme B expression than those which received vehicle alone." (PMID 31671149, 2019). "This approach induced an anti-tumor immune response, as observed via elevated IL-2 and IFNγ secretion." (PMID 30917934, 2019). "For example, IL-1β is required for the polarisation of IFNγ-producing CD8+ T cells; and is also implicated in the immunostimulatory properties of chemotherapy in the generation of anti-tumour γδT cells." (PMID 30538296, 2019). "These CTLs produce an anti-tumor response characterized by IFNγ secretion and exhibit antigen-specific killing of target cells." (PMID 30917934, 2019). "Preclinical data have demonstrated the additive effect of RT and vaccines with an enhanced destruction of tumor cells, the release of TAs, an increase in IFNg production, and a global decrease of the tumor volume." (PMID 30953535, 2019). "Depletion of FAP+ CAFs using transgenic mice with FAP promoter- driven diphtheria toxin receptor (DTR) resulted in tumor regression in an IFNγ and TNFα dependent manner." (PMID 31428105, 2019). "In this context, while cytotoxic T and NK cell activity is dispensable for the antitumor effect, IFNγ-dependent reprogramming of the tumor microenvironment is required." (PMID 31555258, 2019). "Regarding the extrinsic antitumor property, IFNγ plays a pivotal function in stimulating antitumor immunity and promoting tumor recognition and elimination." (PMID 31113461, 2019). "And as expected after performing further analysis between TC negative and TC positive samples in increasing IC subgroups, strong evidence of a hampered IFNγ-PD-L1 axis in tumor cells within the TC0/IC3 subgroup was found." (PMID 31125352, 2019). "Thawed cells preserved their capacity to kill tumour cells also at an E:T ratio of 1:1 and to release a significant level of IFNγ." (PMID 31824502, 2019). "Expression of PD-L1 protein is under the control of inflammatory signals that are typically associated with an adaptive immune response (e.g. interferon gamma [IFNγ]) and can be found on both tumour cells and tumour infiltrating immune cells." (PMID 30986253, 2019). "Next, to determine how responsiveness to IFNγ affects tumor growth and response to checkpoint inhibitors, Ifngr1 was silenced in CMT167 cells using two separate shRNAs against murine Ifngr1 and a nontargeting control vector." (PMID 31133614, 2019).
tumor (continued). "Any perturbation that impacts upon NK cell metabolism impairs the effector function of these cytokine-stimulated NK cells including IFNγ production and tumour cell cytotoxicity." (PMID 31595191, 2019). "In this report, the authors illustrated that ICB administration with either anti-CTLA-4, anti-PD-1, or anti-PD-L1 improved the glycolytic capacity and Interferon-gamma (IFNγ) production of CD8+ tumor-infiltrating T cells." (PMID 31293576, 2019). "NK cells also produce the cytokine Interferon γ (IFNγ) that can directly kill tumour cells as well as serving to communicate to other immune cells, thus orchestrating the immune response." (PMID 31595191, 2019). "MVP promotes IFNγ-mediated signalling, MAP kinase activity and neutrophil degranulation, while NGAL is a tumour-associated antigen involved in cell adhesion and innate immunity." (PMID 31366407, 2019). "Based on these findings, a model can be proposed where IFNγ-producing immune cells increase tumor chemokines to recruit more immune cells that will further induce chemokine expression and so on." (PMID 30873179, 2019). "CircRNA_100085, AK02180, IFNG, ITGA5, and DES were significantly associated with tumor size and TNM." (PMID 30446877, 2019). "All these data demonstrated that LPS/IFNγ-MV carry anti-tumor information that are effective in reducing tumor size in vivo." (PMID 30853898, 2019). "Monocytes have been shown to be cytotoxic to tumor cells in the presence of pro-inflammatory cytokines such as Interferon Alpha, Interferon Gamma, and IL-6." (PMID 30871636, 2019). "M1 macrophages are activated by cytokines such as interferon-γ (IFNγ), IL-12 and they play a crucial role in recruiting T cells to the tumor microenvironment." (PMID 31861720, 2019). "The inducible tumour expression of PD-1 ligands triggered by IFNγ is a significant tumour immune-escape mechanism." (PMID 30723303, 2019). "As well, a tremendous increase of IFNγ secretion was observed when tumor cells were grown as spheroids reflecting a strong NK cell activation mainly dependent on tumor cell/immune cell cross-linking." (PMID 31354732, 2019). "CSF-1 drives TAM differentiation towards an immunosuppressive, tumor-promoting, M2-like phenotype, while IFNγ or GM-CSF promote classically activated M1 macrophages." (PMID 31554173, 2019). "Nevertheless, the primed and boosted CD4+ T cells produced high amounts of the anti-tumor-cytokine IFNγ indicating that in spite of the presence of potentially immunosuppressive T cell subsets effective anti-tumor-activity is generated." (PMID 30956760, 2019). "The first, an ‘immune decoy’ mechanism in which platelets induce the release of soluble NKG2D ligands from the tumour cell to mask detection and actively suppress NK cell degranulation and inflammatory cytokine (IFNγ) production, concomitantly." (PMID 30908480, 2019). "Because IFNγ induces the expression of PD-L1 on tumor cells, we also observed slightly higher PD-L1 levels of the treated tumor tissue." (PMID 31640814, 2019). "Mechanistically, the dual therapy augments intra-tumoral CD8+ tumor-specific T cells and IFNγ mRNA levels as compared to single-agent treatments." (PMID 31244820, 2019). "The TME agent mediating monocyte/macrophage reprogramming was ascribed to be IFNγ secreted by ICT-unleashed tumor-specific T cells." (PMID 31766350, 2019). "The screen revealed two broad classes of ‘hits’— sgRNAs targeting components of the tumor-immune synapse or components of the IFNγ signaling pathway." (PMID 31452512, 2019). "IFNγ production from purified T cells of cured mice was significantly enhanced after encountering A20 tumor cells." (PMID 31307539, 2019). "Activation of the canonical NF-κB pathway in T-cells also increases the amount of tumor-specific IFNγ-producing CD8+ T-cells that account for tumor elimination." (PMID 31349670, 2019).